ENSG00000201316
Synonyms: LOC124902078
Gene: Small nucleolar RNA gene on chromosome 8 (51,015,021 to 51,015,165, forward strand). Ensembl gene ENSG00000201316.
Gene Ontology:
Biological process: RNA processing
Cellular component: nucleolus
Homologues: Paralogues in human: SNORA7A (79% identical), SNORA7B (78% identical).